RB1 (RB transcriptional corepressor 1)
Diseases named in the same sentence as RB1 in open-access papers (continued):
Sharing a sentence is not in itself a finding about the gene and the disease.
glioma (continued). "Namely, the role of secondary mutations in epigenetically driven glioma has only been superficially defined, with an unclear role of key oncogenic driver genes such as EGFR, PTEN, RB1, NF1, TERT, and CDKN2A on modulating the tumor microenvironment." (PMID 37706202, 2023). "Three candidate genes (RAF1, RB1, and SP1) were selected through KEGG pathway analysis, as all three genes were previously found to be associated with glioma pathogenesis." (PMID 36980172, 2023). "On the other hand, high-grade gliomas exhibit altered expression of any of the p16INK4a, cyclin-dependent kinase 4 (CDK4), or retinoblastoma 1 (RB1) genes, resulting in the loss of normal RB1 function." (PMID 35922753, 2022). "One of basic reason of down-regulated expression of RB1 gene in glioma compared with meningioma and pituitary adenoma, can be that number of gliomas are significantly higher in our study cohort compared with other type of brain tumors." (PMID 32373934, 2020). "Since then, many studies have recorded the role of RB1 promoter hypermethylation in different cancers, most commonly in gliomas (the most common cancer of the brain)." (PMID 33143142, 2020). "Expression level of RB1 gene was also correlated with different type of brain tumors and significant down-regulation of RB1 gene was observed in glioma compared with meningioma and pituitary adenomas." (PMID 32373934, 2020). "A study from 2016 found the up-regulation of this miRNA to be closely associated with high-grade glioma and poor overall survival, enhanced migration, and invasion of glioma cells via targeting retinoblastoma tumor suppressor gene 1 (RB1)." (PMID 33255928, 2020). "Deregulation of RB1 gene has been reported in different types of brain tumor such as glioma and meningioma." (PMID 32373934, 2020). "Statistical significant decrease in RB1 mRNA level was observed in brain tumors with anatomical site of glioma (P=0.008) compared with other anatomical sites." (PMID 32373934, 2020). "Overexpression of miR-215 can target the downregulation of the expression of Rb1 protein in gliomas and affect cell proliferation and invasion." (PMID 33083296, 2020). "We dismissed the possibility of glioma given that Zrf-1 positive glial characteristics were scarcely detected in the densely cellular region of rb1-TALEN induced brain tumor tissue." (PMID 28903419, 2017). "In glioma cells, Foxo1 and Rb1 can be inactivated by hyperphosphorylation, and phosphorylated Foxo1 is exported from the nucleus in a CRM1-dependent manner." (PMID 27733172, 2016).
glioma (continued). "We analysed the expression of c-myc, N-myc, L-myc, max and RB1 mRNAs in a panel of human gliomas and glioma cell lines and compared the findings with normal neural cells." (PMID 8286200, 1994). "The Rb1 gene was the most commonly mutated gene, with P/LPSVs were noted in 6/12 (50%) RB patients; P/LPSVs were noted in the NF1 gene in 3 patients: 1/12 (8.3%) patients with RB and 2/3 (66.6%) patients with low-grade glioma." (PMID 40779059, 2025). "We further introduce a segmented block bootstrapping approach to detect focal alternations that achieved 60.9% sensitivity and 98.6% specificity for deletions affecting CDKN2A/B (60.0% and 96.9% for RB1, respectively) in a low-grade glioma cohort from TCGA (n = 239 samples)." (PMID 38244574, 2024). "Among the most frequently mutated genes in adult glioblastomas, no EGFR, PTEN, or RB1 alterations were reported among the most frequently mutated genes in CMMRD-associated gliomas." (PMID 39233831, 2024). "The p16INK4a/CDK4/RB1 pathway often shows alterations in gliomas." (PMID 37626776, 2023). "Identifying these RB1 mutations is relevant to treatment, because tumors harboring inactivation of RB1 are unlikely to respond to CDK4/6 inhibitors, which have been developed and are being investigated as glioma therapy." (PMID 35610333, 2022). "In addition, in vitro analysis showed that enforced miR-215-5p expression promotes migration and invasion of glioma cells by targeting RB1, and vice versa." (PMID 33978071, 2021). "Our candidates also included several genes typically considered TSGs, including CDKN1A (bladder carcinoma, 9.2% in TCGA), KMT2A (kidney carcinoma, 0.6%), MGA (ovarian carcinoma, 1.5%), PTEN (high-grade glioma, 14.2%), RB1 (lung adenocarcinoma, 5.0%), SMAD4 (ovarian carcinoma, 0.5%)." (PMID 34313788, 2021). "Rb1 decreased the apoptotic effects of HSV-1 in a human glioma cell line." (PMID 31693840, 2020). "In contrast, copy number analysis of her DIPG revealed copy number changes frequently seen in gliomas including homozygous loss of RB1, SETDB2, CDKN2A and CDKN2B with no abnormalities in chromosome 17, distinguishing it from the primary medulloblastoma." (PMID 30049282, 2018). "The Rb1 gene, which maps on chromosome 13q14, is mutated in 25% of HGG and the loss of 13q is characteristic of transition from low-grade to intermediate-grade gliomas." (PMID 25147764, 2014). "Contrarily, no case harbored a loss of Rb1 in low-grade MAPK-induced gliomas." (PMID 36900302, 2023). "Therefore, we analyzed the effects of S109 on the phosphorylation of Foxo1 and Rb1 in glioma cells." (PMID 27733172, 2016). "Research demonstrates that PDGFRα signaling is crucial for glioma-like hyperplasia and the preservation of glioma stem cell characteristics via pathways such as PDGFRα/STAT3/RB1." (PMID 40332008, 2025). "Alterations in CDK4/6, CIC, FGFR2/3/4, FUBP1, KIT, MET, NF1, PEG3, RB1, and NTRK2 were additional factors correlated with the survival of different subtypes of gliomas." (PMID 36998447, 2023).
glioma (continued). "Only four genes differentially expressed in both LGG and GBM patients (ERBB1, RB1, ESR1, and KDR), indicating putative role in the regulatory of circadian rhythm pathway alteration in glioma." (PMID 34224318, 2021). "Although IDH-mutant gliomas had lower RB1 expression along with higher methylation, the expression of RB pathway genes CDKN2A and CDKN2B was maintained." (PMID 27852048, 2017). "The expression of the tumor suppressor gene RB1 was moderatelyincreased in ODII tumors (p = 0.06) and significantly enhanced in grade III andIV gliomas (p < 0.01)." (PMID 25791281, 2015). "In “secondary glioma pathway”, gains of PDGFA (1 in LGG and 2 in HGG), PDGFRA (2 in LGG and 2 in HGG) and CDK4 (1 in LGG and 2 in HGG) and RB1 (2 in HGG), and losses of RB1 (1 in LGG and 2 in HGG) are also identified." (PMID 23451178, 2013). "For example, miR-26a that is upregulated in glioma tissues suppresses PTEN, RB1 and MAP3K2/MEKK2 expression and inhibits c-JUNN-terminal kinase-dependent apoptosis." (PMID 24202447, 2013). "A p110 RB1 band was present in the lanes containing: purified RB1 protein, MOLT4 (human leukemia cells), U87 human glioma cells, and RB116 cells." (PMID 23233783, 2012). "All three high grade lines had highly complex genomic profiles and harboured amplifications and deletions at several known cancer genes dysregulated in paediatric glioma, including CCND1, MYC, CDK4, PIK3CA, CDKN2A/B, and RB1." (PMID 19365568, 2009).
glioma (continued). "Also belonging to these key pathways is the gene Retinoblastoma 1 (RB1), which is disrupted in a variety of human solid tumors including pituitary adenomas, esophageal carcinoma, gliomas and ovarian cancer." (PMID 21615919, 2011). "Homozygous losses of CDKN2A/B or RB1 were seen in subgroups of patients, with homozygous RB1 deletions being enriched in H3 G34-mutant diffuse hemispheric gliomas when compared to IDH-wildtype glioblastomas and IDH-mutant gliomas from the GGN cohort (reference cohort 3)." (PMID 39842935, 2025).
glioblastoma (113 papers, 2003 to 2026). The most malignant astrocytic tumor (WHO grade IV). "On the contrary, the mutation of PTEN, EGFR, TTN, NF1, SPTA1 and RB1, which occurred frequently in glioblastoma, were more frequently in PVT1 higher group." (PMID 37202742, 2023). "Whole genome sequencing demonstrated RB1 mutations in 14.3% of bladder cancer cases and 8.3% of glioblastoma multiforme cases." (PMID 37917619, 2023). "Mutations in the cell cycle G1 phase genes CDKN2A/2B, CDK4, and RB1 were mutually exclusive in this series, except for two heterozygous germline RB1 point mutations, and were present in 79.3% of glioblastoma IDH-wild-type cases." (PMID 34572759, 2021). "The tNSC1-3 cell lines also showed a notable deletion in a major part of chromosome 14 including the mouse Rb1 gene that has been reported to be lost or mutated in a subset of human glioblastoma patients." (PMID 33435218, 2021). "For example, the RB1 pathway is inactivated in all glioblastoma tumors but is caused either by somatic RB1 mutations, CDKN2A/B mutations, or CDK4 amplification." (PMID 27126562, 2016). "A clear correlation between loss of RB1 expression and promoter hypermethylation was found in glioblastomas." (PMID 25767620, 2015). "These intragenic deletions included those targeting known tumour suppressors in glioblastoma such as NF1 (17q11.2, n = 2) and RB1 (13q14.2, n = 1), as well as putative novel GBM-associated genes including FAF1 (1p33, n = 2) and MTAP (9p21.3, n = 2)." (PMID 24548782, 2014). "Clinical studies have shown that the dysregulation of RB1 and its pathways has been detected in some glioblastoma and neurodegenerative disease samples." (PMID 38637503, 2024). "For example, the retinoblastoma RB1 gene is a tumor suppressor one, whose status is identified as a determinant of glioblastoma therapeutic efficacy." (PMID 37221474, 2023). "This study aimed to reveal the role of Rb1, Rg1, Rg3, and CK in the drug resistance of glioblastoma." (PMID 36276866, 2022). "This latter can gain Rb1 loss/mutation, CDK4/6 amplification, PDGFRA amplification, or lose CDKN2A and, over the years, becomes IDH-mutated secondary glioblastoma." (PMID 34422883, 2021). "Tumor infiltrating lymphocytes, or TILs, are often enriched in glioblastoma (GBM) with a mesenchymal gene expression signature and are strongly associated with mutations in NF1 and RB1." (PMID 34496929, 2021). "Using netboxr, we identify the PIK3R1 (Module M1) and RB1 (Module M2) modules, each with connected genes that are significantly altered as a set in the glioblastoma (GBM) cancer genomics data from the Cancer Genome Atlas (TCGA)." (PMID 33137091, 2020).